TRIM5 (tripartite motif containing 5)
Diseases named in the same sentence as TRIM5 in open-access papers (continued):
Sharing a sentence is not in itself a finding about the gene and the disease.
glioma (6 papers, 2021 to 2025). A benign or malignant brain and spinal cord tumor that arises from glial cells (astrocytes, oligodendrocytes, ependymal cells). "TRIM5 is upregulated in glioma tissues compared to normal brain tissues, and higher TRIM5 expression is associated with poor prognosis." (PMID 40338274, 2025). "Another study noticed that TRIM5 expression was increased in glioma when compared to normal tissues." (PMID 39353894, 2024). "Combining normal tissue data from the GTEx database with the related data from TCGA, we evaluated the mRNA expression profile of the TRIM family and discovered that TRIM5/21/22/24/28/34/47 were overexpressed in glioma, LGG and GBM tissues." (PMID 37367937, 2023). "To evaluate the prognostic value of TRIM5 in glioma patients, we discovered that the higher TRIM5 expressed, the poorer OS, DSS, PFI they would be." (PMID 37367937, 2023). "Results of differential analysis in our research revealed that the mRNA and protein expression of TRIM5 was higher in gliomas than in normal tissues." (PMID 37367937, 2023). "Specifically, the high expression groups of TRIM5/21/22/28/34/47 had higher immune scores, indicating that these molecules may promote the malignant progression of glioma by regulating the function of immune infiltrating cells." (PMID 37367937, 2023). "Results demonstrated that TRIM5(AUC = 0.938)/17(AUC = 0.829)/21(AUC = 0.934)/22(AUC = 0.867)/24(AUC = 0.990)/28(AUC = 0.898)/34(AUC = 0.949)/TRIM47(AUC = 0.951) exposed excellent accuracy in gliomas." (PMID 37367937, 2023). "TRIM5/21/22/28/34/47 molecules generally showed positive correlations with ICMs, further verifying our idea/intuition that these molecules promote the malignancy of gliomas by inhibiting the function of immune white cells." (PMID 37367937, 2023). "However, since other TRIM molecules mentioned in our study, except for TRIM34 and TRIM5, have already been validated in glioma in vitro experiments from previous studies, we focused our investigations on TRIM34 and TRIM5." (PMID 37367937, 2023). "In addition, survival analysis revealed that the high expression profiles of TRIM5/21/22/24/28/34/47 were associated with poor overall survival (OS), disease-specific survival (DSS) and progress-free interval (PFI) in glioma patients, whereas TRIM17 displayed adverse outcomes." (PMID 37367937, 2023). "At the same time, through GEPIA2, we discovered that the mRNA expression of TRIM5/21/22/24/28/34/47 was significantly up-regulated in different LGG and GBM histological subtypes, while the expression of TRIM17 was down-expressed in diverse gliomas subtypes." (PMID 37367937, 2023). "Until now, almost no one has deeply explored the image of TRIM5 molecules in the occurrence, development, and malignancy of gliomas." (PMID 37367937, 2023). "Moreover, TRIM5 expression also correlated with the clinical characteristics, including WHO grades as well as histological subtypes of the patients with glioma." (PMID 37367937, 2023). "TRIM5 has been reported as a prognostic factor for hepatocellular carcinoma and glioma, which may affect the immune and inflammatory response of virus-infected cells by promoting Lys-63 ubiquitination of MAP3K7/TAK1 complex, but the exact role of TRIM5 in tumors has not been reported." (PMID 38304253, 2023).
measles (4 papers, 2016 to 2022). A highly contagious viral infection caused by the measles virus. "Single nucleotide polymorphisms (SNPs) on TRIM5 and TRIM22 genes have been implicated to play an important role in several infections disease including HIV, HBV, measles and rubella vaccination." (PMID 36042495, 2022). "Single nucleotide polymorphisms (SNPs) at TRIM5 and TRIM22 genes have been implicated in several infections such as HIV, HBV, and measles and rubella vaccination." (PMID 27590274, 2016). "Moreover, the presence of SNPs TRIM5 rs7122620 and TRIM5 rs11820502 correlated, respectively, with increased IL-2 and IL-6 secretion upon measles vaccination." (PMID 33669846, 2021). "However, it has been demonstrated that the synonymous SNPs, TRIM5 rs3824949 and TRIM5 rs7122620, correlated with increased levels of rubella- and measles-specific antibodies in humans upon vaccination against these pathogens." (PMID 33669846, 2021).
multiple sclerosis (4 papers, 2011 to 2018). A progressive autoimmune disorder affecting the central nervous system resulting in demyelination. "Association of multiple sclerosis with the polymorphism rs3802981 located in the first intron of TRIM5." (PMID 21311761, 2011). "The association of TRIM5 with multiple sclerosis is independent confirmation that a retrovirus plays a role in the etiology of MS." (PMID 21311761, 2011). "Therefore, to substantiate the involvement of a retrovirus in multiple sclerosis we sought for linkage disequilibrium between markers in TRIM5 and disease." (PMID 21311761, 2011). "We conclude that HERV-Fc1 and TRIM5 play a role in the etiology of multiple sclerosis." (PMID 21311761, 2011). "In conclusion, we have presented genetic data supporting a role of the retroviral restriction genes, TRIM5, TRIM22 and BST2 in the autoimmune disease multiple sclerosis." (PMID 24066097, 2013). "Strikingly, polymorphisms in TRIM5, TRIM22, and BST2, but not APOBECs or TREX1 were significantly associated to another neuroinflammatory disorder, multiple sclerosis." (PMID 29872426, 2018).
AIDS (3 papers, 2010 to 2024). A syndrome resulting from the acquired deficiency of cellular immunity caused by the human immunodeficiency virus (HIV). "TRIM5 variation and susceptibility to infection has been explored in candidate gene studies in HIV/AIDS cohorts, although reported associations were weak." (PMID 20808775, 2010). "The impact of variation in rhesus macaque TRIM5 has practical implications for preclinical AIDS vaccine research." (PMID 20808775, 2010). "Moreover, these allelic forms of TRIM5 were associated with the extent of loss of central memory (CM) CD4+ T cells and the rate of progression to AIDS in the infected monkeys." (PMID 20107597, 2010). "Similarly, lack of a strong association between TRIM5 variation and infection in HIV/AIDS cohorts may be due to limited variation in human TRIM5 and the fact that HIV-1 has been spreading in human populations for decades." (PMID 20808775, 2010).
coronary artery disease (3 papers, 2020 to 2025). "Notably, rs17305868 and rs11601507 in TRIM5 indicated strong associations with increased platelet counts (p = 9 × 10−10) and coronary artery disease (p = 6 × 10−13), respectively." (PMID 40141459, 2025). "In addition, genetic polymorphisms in the TRIM5/TRIM6 locus have previously been associated with coronary artery disease." (PMID 37370144, 2023). "For example, rs11601507 has no RNA effects, and is associated with TRIM5 protein abundance and with coronary artery disease risk (van der Harst and Verweij, 2018)." (PMID 32773033, 2020).
hepatocellular carcinoma (3 papers, 2020 to 2025). A malignant tumor that arises from hepatocytes. "TRIM5-dependent STR is not specific to cell type, as P90A priming of the hepatoma cell line Huh7 protected those cells from transduction with WT HIV pseudovirus." (PMID 33052966, 2020).
glioblastoma (2 papers, 2024 to 2025). The most malignant astrocytic tumor (WHO grade IV). "In glioblastoma, CD2AP promotes tumour progression through TRIM5-mediated NF-kB signalling." (PMID 41425578, 2025).
malaria (2 papers, 2012). Malaria is a serious and sometimes fatal disease caused by a parasite that commonly infects a certain type of mosquito which feeds on humans. "Carriage of the rs7935564 SNP in the gene encoding TRIM5 (an E3 ubiquitin-ligase) was associated with an increased risk of severe malaria (additive A, OR = 1.273, 95% CI 1.042–1.555, p = 0.02)." (PMID 23144702, 2012). "Allele frequencies for two SNPs in genes that code for IL-13 and TRIM-5 were found to be significantly different between those who have experienced one or more malaria attacks within past 10 years and those who did not." (PMID 22905743, 2012). "Mutations in TRIM5 have been associated with HIV susceptibility in different populations, presumably explained by the ability of TRIM5α to bind HIV virions and target them for proteosomal destruction, but have not previously been linked to malaria susceptibility." (PMID 23144702, 2012).
chronic hepatitis C (1 paper, 2022). "A TRIM5 SNP was associated with increased odds of rapid, early, and sustained virological response after interferon-based therapy in patients with chronic hepatitis C or HIV/HCV coinfection." (PMID 35632621, 2022).
leukemia (1 paper, 2023). A malignant (clonal) hematologic disorder, involving hematopoietic stem cells and characterized by the presence of primitive or atypical myeloid or lymphoid cells in the bone marrow and the blood. "When JMJD3 is knocked out in human leukemia monocytes (THP-1) cells, the expression of key inflammation markers, such as heat shock protein β-1 (HspB1), increased triple motif protein (TRIM5), and glutathione Glycine peroxidase (Gpx), is dramatically decreased." (PMID 36874364, 2023).
liver fibrosis (1 paper, 2016). "TRIM5 and TRIM22 SNPs are associated to increased odds of significant liver fibrosis and SVR after pegIFNα/RBV therapy in HIV/HCV coinfected patients." (PMID 27590274, 2016). "The aim of this study was to analyze whether TRIM5 and TRIM22 polymorphisms are associated with liver fibrosis inflammation-related biomarkers and response to pegIFNα/RBV therapy in HIV/HCV coinfected patients." (PMID 27590274, 2016). "The aim of this study is to analyze whether TRIM5 and TRIM22 polymorphisms are associated with liver fibrosis inflammation-related biomarkers and response to pegylated-interferon-alpha plus ribavirin (pegIFNα/RBV) therapy in HIV/hepatitis C virus (HCV) coinfected patients." (PMID 27590274, 2016).
lung adenocarcinoma (1 paper, 2022). A carcinoma that arises from the lung and is characterized by the presence of malignant glandular epithelial cells. "We found that overexpression of ZNF71 in A549 lung adenocarcinoma cells resulted in the downregulation of multiple components of the intracellular intrinsic and innate immune systems, including dsRNA (OAS1) and dsDNA (STING, pTBK1) sensors and viral restriction factors (TRIM5, SAMDH1)." (PMID 36499305, 2022).
infection (55 papers, 2007 to 2026). The state of being infected such as from the introduction of a foreign agent such as serum, vaccine, antigenic substance or organism. "We also determined TRIM5 polymorphisms, which are known to have influence on susceptibility to SIVsmE543-3 infection." (PMID 34205728, 2021). "In vivo experiments uncovered a central role of TRIM5 proteins in the susceptibility to SIVsmm infection and the evolution of SIV capsid." (PMID 34702294, 2021). "It is important to note that the only animal with a susceptible TRIM5 genotype (r99080) became infected after only a single challenge with SIVsmE660 and maintained high viral loads through the first twelve weeks of infection." (PMID 24651676, 2014). "Several groups reported that the replication of SIVsmE660 was also affected by TRIM5 alleles: these studies suggest that TRIM restriction of this virus can affect acquisition of infection in repetitive “low” dose intra-rectal challenge models." (PMID 23990789, 2013). "Here we showed that selection of TRIM5 resistant SIVsmm capsid mutants at late stages of infection in rhesus macaques expressing restrictive TRIM5 alleles." (PMID 23990789, 2013). "One interpretation of these data is that TRIM5α causes a two-phase block to infection, in which passage of viral DNA to the nucleus is blocked, and then TRIM5 induces the viral core is disassembled by proteasomes." (PMID 23505372, 2013). "Among animals with favorable MHC alleles, the restrictive TRIM5 genotypes were strongly associated with protection from infection, while for the other macaques NAbs and Env-specific CD4+ T-cells were the best correlates." (PMID 23025660, 2012). "A post-hoc analysis of another genetic host factor, TRIM5 polymorphism, revealed that infection-restrictive genotypes were associated with protection against infection in both the vaccine and control groups." (PMID 23025660, 2012). "In the present study, we identify an association between the copy number of activating KIR genes in rhesus monkeys and the control of SIV replication during primary infection in Mamu-A*01– rhesus monkeys that express restrictive TRIM5 alleles." (PMID 22194686, 2011). "Then we assessed the effect of the expression of TRIM5 alleles 6–11 on the survival of the monkeys following infection (log-rank test of equality, Kaplan-Meyer survival curves)." (PMID 20107597, 2010). "Recently, a modest but significant association between TRIM5 genotype and infection in a cohort of SIVmac251-infected macaques was described." (PMID 20808775, 2010). "We then explored the mechanism accounting for the differences in efficiency of restriction of SIVmac239 infection mediated by these different TRIM5 alleles." (PMID 20107597, 2010). "While transduction of cells with the TRIM5 alleles inhibited infection by EIAV, FIV and N-MLV, all evaluated TRIM5 alleles inhibited the infection with comparable efficiency." (PMID 20107597, 2010). "Rhesus monkey B-LCLs homozygous for TRIM5 alleles 7, 9 and 10 were significantly more permissive for SIVmac239 infection." (PMID 20107597, 2010). "We sought to determine whether the expression of particular TRIM5 alleles was associated with particular immune sequelae of infection." (PMID 20107597, 2010). "The TRIM5 gene encodes TRIM5α, a protein that blocks infection of the cell by retroviruses." (PMID 18389077, 2008). "Additionally, CHO cells expressing rhesus macaque TRIM5α or the unique owl monkey variant of TRIM5 (TRIM-Cyp) were also similarly sensitive to HERV-KCON(VSV-G) infection as unmanipulated control cells." (PMID 17257061, 2007). "The discovery of novel aspects of immunogenetic factors, as in the case of TRIM5 polymorphism in retrovirus restriction as part of the innate immune response, will require regular updating to build these into a more complete understanding of host’s ability to impact on infection processes." (PMID 38257982, 2024).
infection (continued). "However, our work raises the possibility that human polymorphisms within the TRIM5 locus could influence resistance to infection with medically important flaviviruses." (PMID 31189110, 2019). "More specifically, we demonstrated that allelic variation in TRIM5 influences the outcome of SIVsm infection in rhesus macaques, and that emergence of SIVsm (as pathogenic SIVmac) required adaptations to overcome the genetic barrier imposed by the most common variant of rhesus macaque TRIM5." (PMID 24098115, 2013). "As TRIM5 in Vero cells blocks infection by HIV‐1–based lentiviral vectors, we used an MLV‐based retroviral vector pseudotyped with NiV G and F proteins." (PMID 41243593, 2026). "Western blotting revealed that SVA infection increased the protein expression of TRIM5 at 12 and 24 hpi, which was positively correlated with the expression of SVA VP2." (PMID 39143491, 2024). "In an abrogation assay, an increasing viral input is added to saturate the limited levels of TRIM5 inside the cell and restore infection." (PMID 39271696, 2024). "Partly due to this mechanism of action, TRIM5 activity becomes saturated at a high multiplicity of infection." (PMID 33524070, 2021). "The premise of TRIM5-based assays is that TRIM5 proteins only recognize the intact capsid and hence inhibit infection of viral particles that remain “coated”." (PMID 34702294, 2021). "While N57A also effectively infected TRIM5-Nup153896–1475-expressing cells, N74D infection was restricted by the TRIM5-Nup153896-1475 fusion protein." (PMID 33477441, 2021). "Because stHIV-A19 has the authentic HIV-1 CA and pig-tailed macaques lack virus-restrictive TRIM5, it is possible by this system to study interaction of HIV-1 CA and cellular factors other than TRIM5 in the course of pathogenic infection in vivo." (PMID 32500043, 2020). "Together, these results are consistent with HIV-1 CA P90A infection stimulating TRIM5-dependent inflammatory gene expression." (PMID 33052966, 2020). "One of these genes, TRIM5, is a retroviral restriction factor that mediates a post-entry block to infection." (PMID 31375773, 2019). "Cells were left untreated or treated with IFNβ for 6 h prior to infection to upregulate TRIM5 expression and induce an antiviral state." (PMID 31189110, 2019). "Infection of IFN-β-treated TRIM5 knockout (T5KO) and control cells with the chimeric vectors allowed us to determine TRIM5α-dependent restriction levels." (PMID 30419009, 2018). "This gene also encodes an antiviral protein (TRIM5, tripartite motif-containing 5), one that is known to act as a blocking factor of HIV-1 reverse transcription thereby limiting the efficiency of the infection in primates." (PMID 26337052, 2015). "This allowed us to observe that the TRIM5-resistant mutant had enhanced acquisition of infection in addition to improved viral replication when compared to wild type virus." (PMID 23990789, 2013). "So far, ovine and caprine TRIM5 have been described genetically, and some of their molecular species have shown the ability to restrict, in vitro, the infection by strain Ev1." (PMID 23917352, 2013). "We developed an experimental approach in which we can monitor TRIM5-induced changes in the viral core at early times after infection, when TRIM5 exerts its effects." (PMID 23505372, 2013). "Fourth, analysis is carried out at an early time (2 h) after infection when events relevant to TRIM5 restriction occur." (PMID 23505372, 2013). "A different vector-based SIV vaccine protected against infection by the robust SIVmac251 strain in a study where the frequencies of restrictive and permissive TRIM5 genotypes were balanced among the groups." (PMID 23025660, 2012). "Such a pattern is consistent with the observation that the impact of TRIM5 genotype in the SIVsmE543-3 infected animals appeared to persist during the weeks following acute infection." (PMID 20808775, 2010).